USP14 (ubiquitin specific peptidase 14)
Diseases named in the same sentence as USP14 in open-access papers (continued):
Sharing a sentence is not in itself a finding about the gene and the disease.
lung carcinoma (28 papers, 2013 to 2025). "In this study, we aimed to study the expression of USP14 in patients with lung cancer and to demonstrate the role of USP14 inhibition and its underlying mechanism in lung tumorigenesis." (PMID 31653087, 2019). "Previous research has shown that USP14 expression is associated with leukemia, colorectal cancer, intrahepatic cholangiocarcinoma, and lung carcinoma and that USP14 inhibits Dengue virus replication." (PMID 27448976, 2017). "6-Gingerol, a phenol extracted from Zingiber officinale Roscoe (Zingiberaceae), suppresses the growth of lung cancer cells by inhibiting USP14 and subsequently regulating autophagy-dependent ferroptosis." (PMID 38292937, 2024). "USP14 controls epidermal growth factor receptor (EGFR) fate in lung cancer by deubiquitinating the endocytic adaptor Eps15." (PMID 39164728, 2024). "The mRNA levels of USP14 were higher in lung cancer tissues compared with the levels in normal lung tissues in The Cancer Genome Atlas (TCGA) database." (PMID 37035133, 2023). "The expression of USP14 in tumor and normal lung tissues from subjects with lung cancer in a hospital cohort was measured by quantitative real‐time polymerase chain reaction (qRT‐PCR) and immunohistochemistry (IHC)." (PMID 37035133, 2023). "A recent study found that USP14 stabilized Beclin 1 to reduce autophagy-dependent ferroptosis induced by 6-Gingerol in lung cancer cells." (PMID 36596780, 2023). "In this study, USP14 was associated with the occurrence of lung cancer and DDP‐resistant lung cancer." (PMID 37035133, 2023). "USP14 mRNA and protein levels were higher in the lung tissues of patients with lung cancer, especially in DDP‐resistant patients, compared with the levels in normal lung tissues." (PMID 37035133, 2023). "The survival rate of lung cancer patients with increased USP14 expression was significantly lower than the survival rate of patients with low USP14 expression." (PMID 37035133, 2023). "Aptamer‐targeted nano‐zinc carriers were loaded with USP14 siRNA to target DDP‐resistant lung cancer cells." (PMID 37035133, 2023). "When lung cancer cells are treated either with USP14 inhibitor or USP14 siRNA, they have decreased proliferation and invasion." (PMID 34689261, 2022). "The nickel complex NiPT, which is a proteasomal DUB inhibitor, inhibits USP14 and UCHL5 and promotes autophagy associated with the ER stress/AMPK/mTOR/S6K regulatory axis in lung cancer cells." (PMID 33919439, 2021). "Genetic or pharmaceutical inhibition of USP14 has been shown to significantly decrease the proliferation, migration, and invasion of lung cancer cells." (PMID 35069211, 2021). "In A549 lung cancer cells, inhibition of USP14 induced ER stress-mediated autophagy by activating JNK1." (PMID 35069211, 2021). "6-Gingerol induces autophagy-dependent ferroptosis in lung cancer cell by inhibiting ubiquitin specific peptidase 14 (USP14) expression." (PMID 34742351, 2021). "In this study, we report that the deubiquitinating enzyme USP14 is highly overexpressed in human lung cancer and USP14 inhibition suppresses cell proliferation, migration, and invasion in lung cancer." (PMID 31653087, 2019). "Conversely, USP14 overexpression in lung cancer cells markedly increases cell proliferation, migration, and invasion." (PMID 31653087, 2019). "To demonstrate the role of USP14 in tumorigenesis, we first examined endogenous USP14 protein in lung cancer cell lines." (PMID 31653087, 2019). "We also demonstrated that as per the TCGA Lung Adeno Carcinoma database, USP14 levels are higher in patients with lung cancer than in normal individuals, and this finding is consistent with our Western blotting data." (PMID 31653087, 2019). "Our findings suggest that USP14 plays a crucial role in lung tumorigenesis and that USP14 inhibitors are potent drugs in lung cancer treatment." (PMID 31653087, 2019).
lung carcinoma (continued). "The downregulation of Usp14 ensured smaller tumor sizes and longer survival in nude mice injected with lung cancer or melanoma cells." (PMID 31456945, 2019). "The aim of this study was to evaluate the prognostic significance of USP14 in patients with lung adenocarcinoma and to define its role in lung cancer cell proliferation." (PMID 23702845, 2013). "The deubiquitinating enzyme USP14 has been identified and biochemically studied, but its role in lung cancer remains to be elucidated." (PMID 23702845, 2013). "Additionally, 6-Gingerol inhibits lung cancer cell growth by targeting USP14 and regulating autophagy-dependent ferroptosis." (PMID 38292937, 2024). "USP14 levels were higher in DDP‐resistant lung cancer compared to DDP‐sensitive lung cancer." (PMID 37035133, 2023). "In addition, USP14 enhances Wnt/β-catenin signaling pathway via stabilizing β-catenin to promote tumor development in lung cancer and hepatocellular cancer." (PMID 36423684, 2022). "Several studies have revealed the versatile roles of USP14 in lung cancer." (PMID 36582601, 2022). "Hence, USP14 plays an essential role in lung cancer and the development of USP14 inhibitors appears to be a potential therapeutic approach for lung cancer." (PMID 35069211, 2021). "The expression of USP14 is upregulated in human lung cancer cells." (PMID 33919439, 2021). "Decreased USP14 elevated the autophagosomes and reduced the survival of lung cancer cell." (PMID 34376189, 2021). "In addition, overexpression of USP14 promotes I-κB degradation despite decreasing polyubiquitinated I-κB levels in MLE12 lung cancer cells." (PMID 34948233, 2021). "The results indicate that 6-Gingerol inhibits lung cancer cell growth via suppression of USP14 expression and its downstream regulation of autophagy-dependent ferroptosis, revealing the function and efficacy of 6-Gingerol as a therapeutic compound in A549 and its possible mechanism of action." (PMID 33281606, 2020). "A recent study has tested IU1-47 in lung cancer and proved that the inhibition of proteasome USP14 by IU1-47 could significantly decrease cell proliferation, migration, and invasion in lung cancer." (PMID 32272746, 2020). "Here, we found that USP14 is highly expressed in patients with lung cancer." (PMID 31653087, 2019). "Therefore, further studies are required to completely understand the functional role of USP14 in lung cancer." (PMID 31653087, 2019). "USP14 inhibition was found to strongly suppress cell proliferation in lung cancer." (PMID 31653087, 2019). "We observed similar results with inhibition of USP14 using IU1-47 in lung cancer cell lines." (PMID 31653087, 2019). "We have demonstrated here that autophagy-induced cell death is involved with USP14 in lung cancer." (PMID 31653087, 2019). "To confirm whether using IU1-47 decreases cell proliferation, invasion, and colony formation in lung cancer, we tested USP14 knockdown using siRNA on A549 and H1299 cells." (PMID 31653087, 2019). "Finally, we investigated the possible role of USP14 in lung cancer proliferation and cell cycle regulation." (PMID 23702845, 2013). "However, the role of USP14 in lung cancer sensitivity to DDP is unclear." (PMID 37035133, 2023). "Thus, we used IU1-47, which is a new small-molecule inhibitor of USP14 in lung cancer cell lines." (PMID 31653087, 2019). "Finally, our research suggests that USP14 inhibitor can be used as a target in lung cancer therapy." (PMID 31653087, 2019). "It has also been reported that the DUB inhibitor NiPT, which also blocks both Uchl5 and Usp14, induces autophagy in A549 and NCI-H1299 lung cancer cell lines." (PMID 39912491, 2025). "We also found that USP14 inhibition significantly increases LC3 II expression and suppresses lung cancer progression." (PMID 31653087, 2019). "We also demonstrated that USP14 inhibitors (IU1-47 and siRNA-USP14) significantly decreased cell proliferation, migration, and invasion in lung cancer." (PMID 31653087, 2019).
lung carcinoma (continued). "Furthermore, we analyzed the RNA levels of USP14 in 517 LUAD and 502 LUSC tumor samples using the transcriptome expression data from lung cancer patients in TCGA." (PMID 32887472, 2020). "Overall, our results demonstrated that USP14 is upregulated in lung cancer and that it could be suppressed by IU1-47, an USP14 inhibitor." (PMID 31653087, 2019). "Endogenous USP14 protein levels were higher in the lung cancer cell lines A549, H460, H1299, H2009, and H3255 than in the normal lung cell line Beas2B but not in the lung cancer cell line H1975." (PMID 31653087, 2019). "To identify the expression of USP14 in lung cancer tissues, we examined the protein levels of USP14 in 74 paired patient-derived lung cancer tissues and adjacent nontumor nontumor lung tissues using Western blotting with an USP14 antibody." (PMID 31653087, 2019). "We found that USP14 is expressed at high levels (68.9%, 51/74) in lung cancer tissues, and its level was significantly different between the nontumor lung tissues and lung cancer tissues." (PMID 31653087, 2019). "Remarkably, USP14 regulated cell proliferation in lung cancer not by apoptosis but by autophagy." (PMID 31653087, 2019).
colorectal cancer (23 papers, 2013 to 2026). A primary or metastatic malignant neoplasm that affects the colon or rectum. "To determine USP14 function in colorectal carcinogenesis, we examined the phenotype using USP14-overexpressing or USP14-deficient colorectal cancer cell lines." (PMID 36693850, 2023). "USP14 is elevated in colorectal cancer patients and is positively associated with JNK protein and downstream gene expression." (PMID 36693850, 2023). "Here, we show a post-transcriptional regulatory mechanism of IDO1 regulated by a proteasome-associated deubiquitinating enzyme, USP14, in colorectal cancer (CRC)." (PMID 36163134, 2022). "Additionally, recent findings highlighted the proteasome-associated deubiquitinating enzyme USP14, as an important target in colorectal cancer (CRC)." (PMID 41262240, 2025). "Similarly, overexpression of cytoplasmic USP14 was confirmed in colorectal cancer tissues and is associated with lymph node metastasis and worse overall survival." (PMID 34089575, 2021). "USP14 regulates the progression of many different tumor types, including colorectal cancer, by mediating cancer cell proliferation, apoptosis, and cell cycle arrest." (PMID 39928282, 2025). "The role of S100A11 in colorectal cancer cell proliferation, migration, and invasion was assessed in the context of USP14 knockdown." (PMID 40374593, 2025). "USP14 inhibitors have shown significant potential in cancer therapy, particularly for colorectal cancer, by suppressing tumour growth, enhancing chemotherapy and radiotherapy effectiveness, and overcoming drug resistance." (PMID 40374593, 2025). "Recently, the USP14‐Ubl domain was found to be critical for USP14 interaction with the IDO1 protein in colorectal cancer." (PMID 38588275, 2024). "An AOM/DSS-induced colorectal cancer model was established to assess the effect of intestinal-specific Usp14 depletion on tumorigenesis." (PMID 36693850, 2023). "The results suggest that USP14 is a pivotal driver of colorectal cancer development and progression." (PMID 36693850, 2023). "In conclusion, Usp14 tends to facilitate colorectal cancer progression by stabilizing JNK and subsequently promoting pathway activation." (PMID 36693850, 2023). "First, we analyzed USP14 expression in The Cancer Genome Atlas (TCGA) and Oncomine datasets, which showed that USP14 was upregulated in colorectal cancer patients." (PMID 36693850, 2023). "Sabates-Bellver and Hong colorectal data from the Oncomine database showed a similar pattern of high USP14 expression in colorectal cancer." (PMID 36693850, 2023). "It was previously shown that USP14 can stabilize JNK to promote colorectal cancer proliferation and can catalyze the deubiquitination of TAZ to drive pancreatic ductal adenocarcinoma progression." (PMID 37686660, 2023). "We revealed an oncogenic role for USP14 in colorectal cancer in vivo and in vitro: USP14 deubiquitinates and stabilizes JNK, which in turn promotes MAPK/JNK signaling cascade activation." (PMID 36693850, 2023). "Our study suggests that elevated expression of USP14 promotes MAPK/JNK signaling by stabilizing JNK, which in turn augments colorectal carcinogenesis, indicating a potential therapeutic target for colorectal cancer patients with increased USP14 expression." (PMID 36693850, 2023). "In summary, we found that USP14 is upregulated and positively associated with JNK in colorectal cancer." (PMID 36693850, 2023). "The AOM/DSS-induced colorectal cancer model verified the oncogenic role of USP14, which extended the evidence showing that USP14 is an oncogene in vivo." (PMID 36693850, 2023). "In summary, USP14 promotes colorectal cancer cell proliferation and migration and enhances colorectal cancer cell viability." (PMID 36693850, 2023). "To further assess the role of USP14 in colorectal cancer tumorigenesis, we generated USP14-knockdown and USP14-knockout DLD1 and RKO cell lines via CRISPR/Cas9-mediated genomic editing." (PMID 36693850, 2023).
colorectal cancer (continued). "To further clarify the tumorigenic role of Usp14 in colorectal cancer in vivo, we generated intestinal-specific Usp14-deleted mice (Usp14fl/fl;Villin-Cre) using Usp14fl/fl conditional knockout mice crossed with intestinal-specific Villin-Cre mice." (PMID 36693850, 2023). "Elevated USP14 expression was connected to clinical stages with liver and lymph node metastases in another investigation of colorectal cancer patients." (PMID 36237424, 2022). "Recent studies showed that USP14 is overexpressed in colorectal cancer and esophageal squamous cell carcinoma (ESCC)." (PMID 31694672, 2019). "Finally, the AOM/DSS-induced colorectal cancer model was used in experiments that further demonstrated the regulation of MAPK/JNK signaling by USP14." (PMID 36693850, 2023). "Our study reveals a new carcinogenic mechanism of USP14, which may be a potential therapeutic target for colorectal cancer." (PMID 36693850, 2023). "USP14 is suspected to play a role in ovarian and colorectal cancers, among other malignancies." (PMID 36237424, 2022). "By analyzing the cBioPortal database, we found that mutations to Ser in USP14 occurred in skin cutaneous melanoma, uterine endometrioid carcinoma, prostate adenocarcinoma, and ovarian cancer, and the mutation of Lys to other amino acids i GPX4 was detected in colorectal cancer." (PMID 38247539, 2024). "Thus, we tested the hypothesis that USP14 promotes colorectal cancer carcinogenesis by targeting JNK for stabilization." (PMID 36693850, 2023). "However, the role of USP14 in colorectal cancer remains to be determined." (PMID 36693850, 2023). "Finally, we revealed a novel mechanism of USP14 in colorectal cancer development and progression." (PMID 36693850, 2023). "Furthermore, high levels of USP14 expression were observed in patients with colorectal carcinoma with lymph node metastasis and liver metastasis, which indicated that USP14 may promote tumor metastasis." (PMID 27448976, 2017). "In this study, we examined PD-L1 expression in various types of immune cells in human colorectal cancer in connection to cancer progression-specific USPs, including USP10, USP12, USP14, USP18, USP32, USP33, and USP39." (PMID 41356798, 2026). "The roles of USP14 and UCHL5 in cancer have indeed been examined in various contexts, including colorectal cancer and chronic myeloid leukemia." (PMID 40804247, 2025). "In colorectal cancer (CRC), knocking down USP14 can inhibit IDO1 expression, enhance CD8+ T cell activity and numbers, and make CRC cells more sensitive to immunotherapy." (PMID 39315102, 2024). "Here, the authors show that deubiquitinase USP14 regulates immune suppression by inducing IDO1 stabilization and suggest USP14 as a potential therapeutic target to improve immunotherapy in colorectal cancer." (PMID 36163134, 2022). "Moreover, noncanonical regulatory mechanisms have attracted attention—for instance, the USP14 inhibitor IU1 has been reported to downregulate IDO1 expression and restore T cell–mediated antitumor responses in colorectal cancer models." (PMID 40666095, 2025). "The mRNA level of USP14 in various colorectal cancer cell lines, including FHC (normal fetal colonic mucosa cell line), HCT116, SW48, DLD1, HT29, RKO, LoVo, HCT115, and SW480 cells, was tested by real-time PCR." (PMID 36693850, 2023).